ATG9B (autophagy related 9B)
Diseases named in the same sentence as ATG9B in open-access papers (continued):
Sharing a sentence is not in itself a finding about the gene and the disease.
tumor (19 papers, 2014 to 2026). "High expression of ATG9B in tumour significantly increased the risk of metastasis and poor prognosis of CRC." (PMID 34131310, 2021). "Previous studies have shown that ATG9B not only regulates cellular autophagy, but is also is correlated with tumour drug resistance, therefore, we selected ATG9B as a potential downstream molecule of CPNE7." (PMID 38526029, 2024). "As expected, there was significantly lower ATG9B protein levels in tumor tissues compared to adjacent normal tissues." (PMID 36262348, 2022). "Simultaneously high expression of ATG9B and MYH9 was closely associated with high risk of tumour lymph node invasion and distant metastasis." (PMID 34131310, 2021). "Taken together, these data demonstrate that ATG9B is positively correlated to tumour metastasis and poor prognosis of CRC patients." (PMID 34131310, 2021). "Taken together, we highlighted the vital role of ATG9B in tumour metastasis by accelerating the formation of FAs in a MYH9-dependent manner during cell migration." (PMID 34131310, 2021). "Up–regulate the expression of ATG9B gene to inhibit tumor cell apoptosis and the formation of tumor microenvironment." (PMID 33013829, 2020). "Tumour-derived EVs containing miR-3091-3p internalised by hepatocytes suppressed autophagy-related protein 9b (Atg9b) expression." (PMID 30682793, 2019). "Therefore, the goal of this study was to define the cellular distribution of ATG9B in two different tumor cell types and to provide insights into its cellular function." (PMID 41811769, 2026). "Similarly, the tumor-suppressive effects of ATG9B and ATG16L1 were found in cervical cancer and epithelial cell tumors, respectively." (PMID 40231206, 2025). "Here, ATG9B as essential for self‐renewal capacity and tumor‐propagation potential is identified." (PMID 35882624, 2022). "This suggests that ASP-3 can be used as an antitumor drug, and its molecular mechanism may be achieved by activating the ATG9B/VEGF signaling pathway to inhibit tumor angiogenesis-mediated cell invasion, which needs further study." (PMID 36532760, 2022). "To date, few studies on the relationship between ATG9B and tumours have been conducted." (PMID 34131310, 2021). "However, to date, very few detailed studies have been performed to delineate the complex relationship between ATG9B and tumour progression." (PMID 34131310, 2021). "Specifically, ATG7 might play a role in tumor promotion, while ATG9B might be a tumor suppressor." (PMID 36262348, 2022). "In tumours, there may also be two or more proteins, which belong to different families, could combine with each other and is similar to the binding manner of ATG9B and MYH9, thus contributing to mutual stabilization of proteins promoting cascade amplification of tumour pathways." (PMID 34131310, 2021). "Furthermore, overexpressing ATG9B enhanced adhesion of tumour cells to FN, while silencing MYH9 could reverse this phenomenon, even in the presence of MG132." (PMID 34131310, 2021). "In addition, other autophagy-related proteins (ATGs), including ATG7, ATG9B, and ATG16L1, also play important roles in tumor suppression." (PMID 40231206, 2025). "Moreover, some tumor-related lncRNAs are regulated by ASP-3, including lncRNA ATG9B, which targets the VEGF signaling pathway." (PMID 36532760, 2022). "Compared with normal tissues, tumor tissues showed significantly higher mRNA levels of the following key autophagy genes: ATG5, ATG7, ATG3, ATG9A, ATG9B, ATG12, AMBRA1, and NBR1." (PMID 32582551, 2020). "The observed effects of Rapamycin on tumor suppression are likely to involve the autophagy process, evidenced by the inhibition of autophagy modulators (TGFβ1, RGS19 and AKT1), autophagosome biogenesis components (AMBRA1, ATG9B and TMEM74) and autophagy byproducts (APP)." (PMID 38276004, 2024).
tumor (continued). "Although AMBRA1, ATG9B and TMEM74 suppression by Rapamycin signals defects in autophagy, evidence suggests the existence of a self-regulatory loop directing tumor cells to death rather than autophagy." (PMID 38276004, 2024).
cancer (17 papers, 2014 to 2026). A tumor composed of atypical neoplastic, often pleomorphic cells that invade other tissues. "Loss of ATG9A and ATG9B genes or disruption of the autophagy pathway is associated with a vast variety of cancers." (PMID 40949798, 2025). "Deregulating autophagy by the frameshift mutations of Atg2B, Atg5, Atg9B and Atg12 is involved in cancer development." (PMID 34829743, 2021). "Some autophagy-related genes (ATGs), such as ATG2B, ATG5, ATG9B, and ATG12, have been reported to contain frameshift mutations in cancer, implicating the potential contributions to tumorigenesis and cancer metastasis." (PMID 38338839, 2024). "WT mouse CRIPSCs also had higher expression of the genes related to stem cells (Psca, Atg9b, Sox2, Sox9), cell cycle (Cdk6), mammary luminal progenitor cells (Notch3 and Notch1), and cancers." (PMID 35841025, 2022). "By mining the HNSCC single-cell database, we further proved that ATG9B mainly functions in cancer cells through enhancing the epithelial phenotype of cancer cells." (PMID 36262348, 2022). "Specifically, ATG9B was a protective factor in HNSCC patients through downregulating cancer cell EMT, and ATG7 was correlated with the immunosuppressive environment in HNSCC." (PMID 36262348, 2022). "For example, Atg9b plays an essential role in stem cell maintenance and cancer development under the regulation of the Wnt/β-catenin signaling pathway." (PMID 35841025, 2022). "Collectively, these results indicate that high ATG9B expression is positively correlated with the epithelial phenotype of single cancer cells through mining the HNSCC single-cell database." (PMID 36262348, 2022). "WIPI2, ATG9B, MAP1LC3A, and RB1CC1 have higher frequencies of gain mutation frequencies in the pan-cancer analysis." (PMID 34636718, 2021). "Numerous studies have shown that other ATG genes, including ATG2B, ATG5, ATG9B, ATG12, and ATG16L1, are also associated with human different cancers." (PMID 34443541, 2021). "A number of studies on the ATG genes relevance to human cancers showed that other ATG genes are also oncogenically associated, including ATG2B, ATG5, ATG9B, ATG12 and ATG16L1." (PMID 31969156, 2020). "Several studies have reported that the transmembrane, autophagic lipid scramblase ATG9B is altered in multiple cancers, suggesting that this dysregulation could contribute to oncogenesis." (PMID 41811769, 2026). "Similarly, promoter hypermethylation of ATG4D, ATG2B, ATG9A, and ATG9B genes has been demonstrated in most invasive ductal carcinomas (IDC), and this enhanced methylation was associated with the cancer grade, reduced gene expression, and lymph node metastasis." (PMID 40949798, 2025). "Mechanistically, single-cell analysis revealed that ATG9B increased the epithelial phenotype of cancer cells but did not influence EMT signaling pathways." (PMID 36262348, 2022). "The mutations with mononucleotide repeats have been found in ATG2B, ATG5, ATG9B, and ATG12 genes in gastric and colorectal cancers, which may be involved in cancer development by dysregulating autophagy." (PMID 34443541, 2021). "The frameshift mutations with mononucleotide repeats have been found in ATG2B, ATG5, ATG9B and ATG12 genes in gastric cancer and colorectal cancer, which may be involved in cancer development by deregulating the autophagy process." (PMID 31969156, 2020). "We found that ATG9B was mainly expressed in cancer cells and not in immune and stromal cells." (PMID 36262348, 2022). "Although the PI3K-mTOR pathway has been reported to negatively regulate autophagy in various cancers including GBM30–32, ATG9B mRNA expression was not affected by either rapamycin or LY294002." (PMID 32943609, 2020).
infection (3 papers, 2012 to 2016). The state of being infected such as from the introduction of a foreign agent such as serum, vaccine, antigenic substance or organism. "One transcript (ATG9B) involved in autophagy was significantly decreased in expression following infection." (PMID 27677841, 2016). "Both infectious HIV and AT-2-inactivated HIV increased the transcription of ATG9B, UVRAG, and MCOLN1 suggesting activation of TFEB by HIV does not require productive infection." (PMID 26115100, 2015).
bacterial infection (1 paper, 2024). "Future research should include lung organoid models or in vivo studies to validate the ATG9B function during bacterial infection." (PMID 38706859, 2024). "Therefore, we sought to confirm whether ATG9A and ATG9B are critical for autophagy induction during bacterial infection." (PMID 38706859, 2024).
ATG9B also shares sentences with these, for which no sentence is quoted: colon tumor (1 paper); diabetic nephropathy (1); head and neck squamous cell carcinoma (1); infertile (1); lentivirus infection (1); Parkinson disease (1); prostate carcinoma (1); protein folding disorders (1); renal dysfunction (1); tuberculosis (1).